ARID1A (AT-rich interaction domain 1A)
Diseases named in the same sentence as ARID1A in open-access papers (continued):
Sharing a sentence is not in itself a finding about the gene and the disease.
bladder cancer (53 papers, 2012 to 2026). "Studies show that PIK3IP1 protein is upregulated in ARID1A‐deficient bladder cancer cells and inhibits the PI3K signalling pathway." (PMID 39779467, 2025). "In bladder cancer, data from the CheckMate-275 and IMvigor210 trials demonstrated that patients with ARID1A mutations and high CXCL13 expression had favorable outcomes following ICI treatment." (PMID 40406143, 2025). "Chromatin regulation genes, including KDM6A, KMT2D, EP300, and ARID1A, show high rates of mutation in bladder cancer, as demonstrated here and in multiple cohort studies." (PMID 41373802, 2025). "ARID1A‐deficient bladder cancer cells are sensitive to PI3K inhibitors, and combined use with EZH2 inhibitors can achieve synergistic anti‐tumour effects." (PMID 39779467, 2025). "ARID1B, as a homologous subunit of ARID1A, can potentially serve as a target for ARID1A‐mutated bladder cancer." (PMID 39779467, 2025). "ARID1A mutation leads to self-inactivation but induces the occurrence of bladder tumors and affects the immune invasion process of bladder cancer, and ARID1A mutation is associated with poor prognosis." (PMID 38584203, 2024). "Bladder cancer patients had P153A mutations in the ARID1A/1B subunit before and after resistance to pazopanib." (PMID 39697230, 2024). "In ARID1A-deficient tumors, such as bladder cancer, the loss of ARID1A leads to a transcriptional-translational conflict, resulting in an accumulation of pro-proliferative transcripts while inhibiting eEF2 function." (PMID 39707196, 2024). "The translational inhibitor homoharringtonine (HHT) was used to treat bladder cancer organoids that were either ARID1A deficient or proficient." (PMID 37743426, 2023). "Further, reverse translational studies demonstrated that mice bearing CXCL13-ablated tumors were resistant to ICB, whereas loss of ARID1A improved sensitivity to anti-PD-1 therapy in a murine model of bladder cancer." (PMID 36980292, 2023). "In sum, clinical applications targeting these molecules in ARID1A-deficient bladder cancers should be pursued." (PMID 35852858, 2022). "In conclusion, ARID1A-deficient bladder cancers are dependent on PI3K signaling, which can be pharmacologically targeted with EZH2 and/or PI3K inhibitors." (PMID 35852858, 2022). "The results herein suggest that subgroup analyses of these and other EZH2 inhibitor trials should focus on patients with bladder cancer with ARID1A-deficient tumors." (PMID 35852858, 2022). "To determine if PIK3IP1 upregulation is necessary and sufficient for GSK-126 sensitivity in ARID1A-deficient bladder cancer cells, we generated an array of dual ARID1A/PIK3IP1 stable knockdown cells and ARID1Akd/PIK3IP1 stable overexpression cells." (PMID 35852858, 2022). "PIK3IP1 upregulation is necessary and sufficient for GSK-126–mediated cell death in ARID1A-deficient bladder cancer cells." (PMID 35852858, 2022). "Using lysates of 3 matched pairs of human bladder cancers and adjacent normal tissue, as well as 6 unmatched samples, we determined that tumors deficient in ARID1A protein had elevated PIK3R3 and pAKT levels." (PMID 35852858, 2022). "Chromatin modifiers are frequently mutated in bladder cancer, with ARID1A-inactivating mutations present in about 20% of tumors." (PMID 35852858, 2022). "For various bladder cancer cell lines with ARID1A-truncating mutations or shRNA-mediated depletion, our experiments revealed that EZH2 inhibition is synthetically lethal for bladder cancer cells with ARID1A deficiency." (PMID 35852858, 2022). "Recurring likely pathogenic mutations in ultra-mutated bladder cancers occur in several epigenetic modifiers, such as ARID1A in six cases and in one or more lysine methyltransferases in seven cases." (PMID 35323317, 2022). "Goswami and colleagues have recently shown that ARID1A mutation in combination with immune cytokine CXCL13 expression predicts response to immune checkpoint inhibitors in metastasized bladder cancers." (PMID 33227989, 2020).
bladder cancer (continued). "Several additional cancers, including bladder cancer and uterine corpus endometrial carcinoma, have a high frequency of mutations effecting the genes encoding ARID1A/B." (PMID 30431433, 2018). "As current ARID1A protein expression data in bladder cancer are inconsistent and incomplete we examined if the frequency of truncating ARID1A mutations translates into a similar frequency of cases showing ARID1A protein loss." (PMID 30138427, 2018). "Recently however a report in patients with bladder cancer found that ARID1A/BAF250a deficient tumors are associated with a more aggressive phenotype." (PMID 24559118, 2014). "We identified a truncating mutation in ARID1A through the initial analysis of 2 bladder cancer exomes." (PMID 23650517, 2013). "We found ARID1A mutations to be mainly truncating mutations (77%) in patients with bladder cancer." (PMID 40170512, 2025). "Interestingly, ARID1A mutations are especially prevalent in bladder cancer with frequencies of 15–25%." (PMID 40170512, 2025). "Finding truncations to be the most common mutation, we generated loss‐ and gain‐of‐function models to conduct RNA‐Seq, interactome analyses, Omni‐ATAC‐Seq, and functional studies to characterize ARID1A‐affected pathways potentially suitable for the treatment of ARID1A‐deficient bladder cancers." (PMID 40170512, 2025). "As ARID1A mutations can already be observed in early bladder cancer lesions, it is important to address the consequences of ARID1A deregulation as it might help to understand how early lesions progress towards muscle‐invasive disease with poor prognosis." (PMID 40170512, 2025). "Moreover, these ARID1A alterations frequently coincide with high tumor mutational burden (TMB) subtypes of bladder cancer." (PMID 40918525, 2025). "We hypothesized that bladder cancer cells with ARID1A mutations would show sensitivity to EZH2 inhibition that could be utilized as a therapeutic target for patients with ARID1A-deficient bladder cancer." (PMID 35852858, 2022). "Furthermore, ARID1A-deficient bladder cancer was sensitive to combination therapies with EZH2 and PI3K inhibitors in a synergistic manner." (PMID 35852858, 2022). "Thus, we confirmed that sensitivity of bladder cancer cells to EZH2 inhibition is dependent on ARID1A deficiency." (PMID 35852858, 2022). "Thus, there is a rationale to repurpose EZH2 inhibitors for the pharmacologic treatment of patients with bladder cancers harboring somatic truncating mutations in ARID1A." (PMID 35852858, 2022). "Investigating the mechanisms of EZH2 sensitivity in ARID1A-deficient bladder cancer cells." (PMID 35852858, 2022). "Furthermore, ARID1A-mutated (herein referred to as ARID1Amut) bladder cancers expressed high levels of EZH2, consistent with previous findings that EZH2 expression is upregulated in bladder cancer." (PMID 35852858, 2022). "Importantly, the percentage of cases showing ARID1A protein loss was positively correlated with increasing stage and grade of bladder carcinomas that is partially in concordance with recently published work." (PMID 30138427, 2018). "Finally, we investigated the putative dependence of ARID1A-depleted and ARID1A-mutated urothelial cells on EZH2 using in vitro models for bladder cancer." (PMID 30138427, 2018). "Moreover, amounts of EZH2 protein and H3K27me3 were not significantly different, comparing urothelial bladder carcinomas strongly expressing ARID1A protein (median Remmele score: 12) to bladder cancer cases exhibiting ARID1A protein loss or only residual ARID1A expression (median Remmele score: 0)." (PMID 30138427, 2018). "Bladder cancer PDOs and normal organoids with ARID1A depletion were established and analyzed alongside public datasets to identify dysregulated molecular effectors." (PMID 41503026, 2026). "Intending to describe the impact of ARID1A on bladder cancer development, we correlated our datasets from the Omni‐ATAC‐Seq and the RNA‐Seq experiments in the UROtsa model." (PMID 40170512, 2025).
bladder cancer (continued). "When ARID1A gene mutation and high expression of CXCL13 are present in bladder cancer, the sensitivity to immune checkpoint therapy is increased." (PMID 39779467, 2025). "In the context of bladder cancer, dysregulation or reduced expression of the SWI/SNF complex and its specific subunits such as ARID1A and SNF5 is closely linked to tumour progression, offering a novel therapeutic target." (PMID 39779467, 2025). "To understand the consequences of the high prevalence of ARID1A mutations in cancer, we based our analysis on MSK (Memorial Sloan Kettering) cancer panel data as of 2022, containing 1659 bladder cancer samples from 1244 patients." (PMID 40170512, 2025). "About 20% of bladder cancers have truncating and inactivating mutations in the AT-rich interactive domain 1A (ARID1A) gene, a member of the SWI/SNF chromatin modifying complex, making it one of the most frequently mutated epigenetic genes in bladder cancer." (PMID 35852858, 2022). "ARID1A alterations were most frequent in endometrial (21.3% of patients) and bladder cancer (12.9% of patients)." (PMID 36077815, 2022). "The most frequently mutated genes in the chemo-naïve samples were well-established bladder cancer–associated genes: FGFR3 (70%), KMD6A (47%), PIK3CA (38%), KMT2D (26%), and ARID1A (23%)." (PMID 34934968, 2021). "Compared to the ATM-WT group, ARID1A and TTN mutations were significantly upregulated in the ATM-MT group in the immunotherapy cohort and the TCGA-Bladder cancer cohort, respectively." (PMID 32922441, 2020). "In contrast to current data in bladder cancer, we even observed an increase in the colony forming ability of EZH2-depleted J82 cells that was more pronounced in the ARID1A-deficient background." (PMID 30138427, 2018). "As current ARID1A protein expression data for bladder cancer are inconsistent and incomplete, a comprehensive immunohistochemistry (IHC)-based ARID1A protein expression analysis including carcinoma in situ (CIS) cases was conducted for the first time." (PMID 30138427, 2018). "In line with our assumption, we observed strongly reduced ARID1A mRNA and protein expression in the two bladder cancer cell lines HT1376 and JMSU-1, both harboring a homozygous frameshift mutation in the ARID1A gene as validated by Sanger sequencing." (PMID 30138427, 2018). "Future studies should validate these preliminary observations by including ARID1A-mutated and SWI/SNF wildtype bladder cancer cells." (PMID 30138427, 2018). "ARID1A, a newly identified tumor suppressor gene which encodes a member of the SWI/SNF complex, has a high mutation frequency in bladder cancer, uterine endometrioid carcinoma, ovarian endometrioid and clear cell carcinoma." (PMID 22808142, 2012). "Cells with ARID1A deletion in bladder cancer are more sensitive to EZH2 inhibitors." (PMID 39779467, 2025). "The main intent of our study was to better define the role of ARID1A in human bladder cancer." (PMID 40170512, 2025). "Beyond KDM6A, other genes involved in epigenetic regulation, including KMT2C (Lysine N-methyltransferase 2C), KMT2D (Lysine N-methyltransferase 2D), and ARID1A (AT-rich interactive domain-containing protein 1A), also display aberrant expression patterns in bladder cancer." (PMID 40600050, 2025).
bladder cancer (continued). "In the context of bladder cancer, the lack of ARID1A protein is associated with tumour grade and stage." (PMID 39779467, 2025). "In summary, bladder cancer’s alterations in histone modification pathways–whether via mutation (KDM6A, ARID1A, KMT2D) or overexpression (EZH2, HDACs) – are a central component of its biology and interact with aging." (PMID 40918525, 2025). "However, while PIK3IP1 protein levels are increased in response to GSK-126 in ARID1Adef cells in both OCCC and bladder cancer, the effects of ARID1A levels on PIK3IP1 expression are opposite between the cell types." (PMID 35852858, 2022). "To investigate its effect on proliferation of ARID1Amut bladder cancer cells, we performed viability and proliferation assays using cell lines with and without mutations in ARID1A." (PMID 35852858, 2022). "The loss of ARID1A expression has been associated with poor prognosis, and its mutations confer bladder cancer non-stem cells the self-renewal." (PMID 36399105, 2022). "Next, we sought to determine whether ARID1A deficiency correlated with PIK3R3 upregulation and PI3K/AKT pathway activation in human bladder cancers." (PMID 35852858, 2022). "ARID1A knockdown induces GSK-126 sensitivity in ARID1Awt bladder cancer cells." (PMID 35852858, 2022). "Yang using single-cell sequencing of specimens from three bladder cancers identified six genes not previously found in bladder cancer and revealed that co-mutations in ARID1A, GPRC5A and MLL2 enhanced the self-following ability of bladder cancer cells." (PMID 34895349, 2021). "Moreover, chromatin remodeling genes, such as ARID1A and KDM6A were frequently mutated in bladder cancer." (PMID 33407469, 2021). "According to current European Medicines Agency (EMA)-approved guidelines for first line therapy of bladder cancer with pembrolizumab (CPS ≥ 10) and atezolizumab (IC-score ≥ 2/IC ≥ 5%), a single ARID1A-mutated cancer (1/3) was identified to be potentially eligible for atezolizumab first line therapy." (PMID 33227989, 2020). "Consistent with our study, Wang and colleagues demonstrated that ARID1B depletion inhibits proliferation in bladder cancer cell lines without ARID1A mutation." (PMID 31796878, 2019). "Our data do not support ARID1A-deficiency as predictive biomarker for EZH2-inhibitor treatment response in bladder cancer underlining the need for future bladder cancer-specific, drug screens for successfull discovery of ARID1A-deficiency-based targeted drugs." (PMID 30138427, 2018). "In summary, ARID1A truncating mutations, potentially translating into ARID1A protein loss in a subset of high-grade bladder cancers, are the most common SWI/SNF genetic alterations in bladder cancer." (PMID 30138427, 2018). "Other bladder cancer cells (T24, RT-112, and 5637) did not have mutations in the ARID1A gene." (PMID 35852858, 2022). "ARID1A‐mutated bladder cancer cells exhibit sensitivity to PI3K inhibitors; thus combining EZH2 inhibitors with PI3K inhibitors can yield a synergistic anti‐tumour effect, consequently, ARID1A mutated bladder cancer may be treated with EZH2 and/or PI3K inhibitors." (PMID 39779467, 2025). "This analysis was recapitulated in preclinical studies using bladder cancer PDX models with low, medium, and high levels of ARID1A protein expression." (PMID 37743426, 2023). "The IC50s for ARID1Amut bladder cancer cell lines HT1376 (2.5 μM) and VM-CUB1 (2.8 μM) were much lower than ARID1A WT (ARID1Awt) cell lines T24 (8.3 μM), 5637 (7.6 μM), and RT112 (7.8 μM)." (PMID 35852858, 2022).
bladder cancer (continued). "Bladder cancer samples of the squamous cell type show a lack of ARID1A protein and elevated levels of PD‐L1 expression, indicating potential benefits from immune checkpoint inhibitor therapy for these patients." (PMID 39779467, 2025). "ARID1A-depletion did neither increase EZH2 protein or trimethylated H3K27 levels in vitro nor did ARID1A expression correlate with EZH2 or H3K27me3 amounts in human bladder carcinomas." (PMID 30138427, 2018). "In accordance with the in vitro data, we did not observe differential EZH2 mRNA amounts comparing bladder carcinomas of the TCGA 2017 data set either showing high ARID1A mRNA levels or low ARID1A mRNA expression." (PMID 30138427, 2018). "The absence of the ARID1A protein in bladder cancer is related to the tumour grade and stage." (PMID 39779467, 2025). "In the setting of bladder cancer, the absence of ARID1A could potentially impact the regulation of the cell cycle‐associated gene p21, leading to potential alterations in the growth and propagation of tumour cells." (PMID 39779467, 2025). "Thus, our studies suggest that bladder cancers with ARID1A mutations can be treated with inhibitors of EZH2 and/or PI3K and revealed mechanistic insights into the role of noncanonical PI3K constituents in bladder cancer biology." (PMID 35852858, 2022). "Moreover, we did not observe a correlation of ARID1A expression with EZH2 or H3K27me3 amounts in human bladder carcinomas." (PMID 30138427, 2018). "Next, we selected three urothelial bladder cancer cell lines harboring ARID1A truncating mutations, namely HT1376, JMSU-1, VM-CUB-1 and compared their GSK126 treatment response to three bladder cancer cell lines (J82, RT112, SCaBER) without SWI/SNF complex gene alterations." (PMID 30138427, 2018). "Many studies have investigated ARID1A mutations as prognostic markers in a multitude of different cancers, such as OCCC, as well as breast, gastric and bladder cancer, but to date, none have demonstrated a consistent prognostic significance of ARID1A mutational or expressional status." (PMID 24036443, 2013).